GFAP (glial fibrillary acidic protein)
Diseases named in the same sentence as GFAP in open-access papers (continued):
Sharing a sentence is not in itself a finding about the gene and the disease.
glioma (continued). "Resident astrocytes show reactive response with upregulation of glial fibrillary acidic protein (GFAP) and MMPs in a co-culture with glioma cells U87." (PMID 30286133, 2018). "The GMT, a crucial process in glial tumor progression, is characterized by the reduction of glial markers (GFAP, which is also used as an astrocytic lineage-specific marker) in exchange for increased expression of mesenchymal markers, such as vimentin." (PMID 30583471, 2018). "The double marker GFAP+/SVN+ subpopulation of CD9+ exosomes was much higher in glioma patients (range 0.6 – 27.2%; mean = 6.8%) than in controls (range 0.0 – 0.1; mean = 0.03%), a 227-fold difference." (PMID 29383115, 2017). "Histologically, the tumours were similar to those generated in the orthotopic implantation studies, and were positive for the glioma markers GFAP and Olig2." (PMID 28695888, 2017). "In conclusion, gene amplifications specifically gene amplifications of DDB1, EGFR, MDM4 and GFAP can provide information about the cell types and the degree of heterogeneity at the origin of glioma stem-like cells." (PMID 28415661, 2017). "Accompanied by downregulation of CD133/ABCG2 and upregulation of glial fibrillary acidic protein, bELE was shown to decrease the formation of spheres and inhibit the proliferation of glioma stem cells both in vitro and in vivo." (PMID 28297578, 2017). "Western blot results further confirmed that QUE significantly up-regulated MBP expression, but down-regulated vimentin (a marker for glioma) and GFAP expression." (PMID 28415586, 2017). "A high level of proteins in the NOTCH signaling pathway and GFAP was commonly seen in both neuronal-glial stem/precursor and glioma stem-like cells, which is consistent with the neural stem cell phenotype of cells expected for NS-cultures of GBM." (PMID 29113349, 2017). "Immunocytochemistry (ICC) results indicated that the neural progenitor marker NESTIN, post-mitotic neuron marker TuJ 1, and glial cell marker GFAP were expressed in U87 glioma cells." (PMID 28837560, 2017). "This implies that increasing noise strength in signal transduction can induce bifurcation of cyclin D1 degradation, which renders some glioma cells insensitive to drug treatment and induces heterogeneous activation of GFAP." (PMID 27515956, 2016). "In the vehicle-treated group, the obvious suppression of GFAP expression and an elevated proliferative index indicated the progressively malignant biological behavior of glioma cells." (PMID 27471070, 2016). "Gliomas are apparently developed from GFAP-positive neural stem cells, and remain GFAP-positive after differentiation inhibition." (PMID 27145078, 2016). "For instance, vimentin forms heteropolymeric filaments with desmin in vascular smooth muscle tissue, with glial fibrillary acidic protein (GFAP) in glioma cells and with neurofilaments." (PMID 27120621, 2016). "Immunohistochemistry (IHC) in samples from 74 patients revealed that GFAP expression (a marker of glioma cell differentiation) decreased, while the levels of FMRP and Ki67 increased with grade." (PMID 27683117, 2016). "Double immunofluorescent stainings deciphered GFAP-positive glioma cells as major source of LC3B punctae formation next to necrotic foci, whereas Iba1-positive microglia/glioma-associated macrophages were mainly devoid of LC3B expression." (PMID 26956048, 2016). "GFAP expression co-localized with HiF-1α with high levels in the glioma cells surrounding the blood vessels." (PMID 26689994, 2016). "The apparent Hill coefficients of the simulated dose-response curves for cyclin D1 and GFAP with respect to CT were 40 and 43, respectively, indicating strong ultrasensitivity in the response of glioma differentiation to drug treatment." (PMID 27515956, 2016).
glioma (continued). "Here, we demonstrate the asymmetric distribution of the main astrocytic intermediate filament, namely the glial fibrillary acid protein (GFAP), in mitotic glioma multipotent cells isolated from glioblastoma (GBM), the most frequent type of brain tumor." (PMID 26953813, 2016). "In such studies, Glial fibrillary acidic protein (GFAP) is applied as a reliable marker for evaluating the differentiation of glioma cells." (PMID 27515956, 2016). "As before we confirmed that mNS GSC have a higher expression level of the stem cell markers CXCR4, MELK, PTCH, CD44, CD133, MSl1 and CD90, while GL261 GDC expressed higher level of the differentiated glioma marker glial fibrillary acidic protein (GFAP)." (PMID 27073883, 2016). "This is an unusual pattern of expression, with cytokeratin immunopositivity suggesting a meningioma and GFAP immunopositivity suggesting a glioma." (PMID 26155457, 2015). "Based on literatures, the astroglial lineage-specific promoter GFAP, the tumor-specific promoter Survivin, and the glioma-specific promoter HMGB2 were chosen as candidates." (PMID 26074975, 2015). "For example, DCX is a differentiation-based treatment in vivo for glioma, where DCX induces terminal differentiation of glioma cells via a DCX/GFAP (glial fibrillary acidic protein) pathway." (PMID 26793044, 2015). "Both human and mouse models of glioma can lose GFAP expression with tumor progression either through epigenetic regulation or tumor cell dedifferentiation." (PMID 25644510, 2015). "For example, the expression levels of Notch1 and GFAP were high in low-grade glioma and differentiated glioma cells but were low in high-grade glioblastoma cells and GSC spheres." (PMID 26563263, 2015). "Stainings of H&E and astrocyte marker GFAP were also performed on both glioma and normal brain tissue samples." (PMID 26452219, 2015). "HBA, HBD and HCD2 positively correlated with high-grade gliomas; GFAP, PHP14, 6PGL, PSD13, PEA15, TPIS, CRYAB_b, IPYR and IDH3A correlated with low-grade tumors; on the other hand, NFM, CN37, NDUS1 and MDHC negatively correlated with tumor samples." (PMID 25050814, 2014). "Immunohistochemical staining of GFAP was used to evaluate the differentiation level of the glioma cells." (PMID 25163530, 2014). "The v-Src transgenic mice, in which v-Src expression is under the control of the GFAP promoter, developed glial tumors with morphological and molecular characteristics that mimic human glioblastoma multiforme (GBM)." (PMID 24819299, 2014). "In order to test the presence of this specific astrocytic marker in the glioma cells from 12 V-Ha-Ras transgenic mice, we performed immunohistochemistry (IHC) for GFAP at different passages (8th, 70th, and 100th)." (PMID 25425962, 2014). "The network also contained GFAP, upregulated in young GBM, which has long been considered a fundamental and diagnostic feature of glioma." (PMID 24838487, 2014). "Another group reported an upregulation of the astrocyte marker glial fibrillary acidic protein (GFAP) and a downregulation of the mesenchymal marker vimentin as well as reduced proliferation of glioma cell lines upon Notch inhibition." (PMID 25601901, 2014). "Spinal cord (SC) ependymomas are well-delineated gliomas characterized by prominent glial fibrillary acidic protein (GFAP) expression." (PMID 24817309, 2014). "In glial tumors, GFAP expression is frequently lost with increasing grade of malignancy, suggesting that GFAP is important for maintaining glial cell morphology or regulating astrocytoma cell growth." (PMID 24971310, 2014). "Next, we studied the correlation between DcR3 expression and glioma differentiation, which was evaluated by histological features and GFAP staining." (PMID 24741354, 2014). "The peripheral glioma marker GFAP was increased in the tumoural animals and significantly higher in the male group compared to the females (38.04 ± 7.22 vs. 2.25 ± 0.03, P < 0.01)." (PMID 26116110, 2014).
glioma (continued). "Anti-GFAP antibodies in brain tumors of astrocytic origin (such as glioma and glioblastoma) have also been reported." (PMID 24667434, 2014). "In summary, transposon mobilization in the GFAP compartment was insufficient to drive glioma formation." (PMID 25423036, 2014). "The expression level of GFAP is an important index to assess the differentiation level of glioma cells." (PMID 25163530, 2014). "Cells from glioma spheres were grown in serum-containing medium to induce differentiation before they were stained for specific markers for astrocytes (GFAP), oligodendrocytes (MBP) and neurons (βIII-tubulin)." (PMID 24819299, 2014). "In the studies of tumor-specific promoters, the GFAP promoter exhibited glioma-specific hNIS expression in the U87 and U251 cells and did not cause hNIS gene expression in MRC-5 normal cells." (PMID 23420532, 2013). "Due to its specificity and abundance, GFAP has become the most commonly used marker for astrocytes and a target of anti-glioma therapy." (PMID 23420532, 2013). "In the present study, we constructed and evaluated the potential functional and therapeutic effectiveness of a recombinant adenovirus Ad-GFAP-hNIS carrying the hNIS gene controlled by the GFAP promoter in U251 and U87 glioma cell lines." (PMID 23420532, 2013). "The GFAP promoter restricts the expression of the transfected hNIS gene to glioma cells and thus maximizes the glioma-specific uptake, while minimizing the non-specific uptake of radioiodine." (PMID 23420532, 2013). "Among consistent findings in the glial tumors was expression of glial fibrillary acidic protein, variably sized regions of necrosis, and high mitotic activity." (PMID 23260029, 2013). "GFAP immunoreactivity also confirmed that C6 glioma cells were differentiated into astrocytes successfully by IL-6 treatment." (PMID 23451161, 2013). "In the present study, we developed and evaluated the potential functional and therapeutic effectiveness of an adenovector incorporating the hNIS gene and the GFAP promoter in glioma cell lines." (PMID 23420532, 2013). "Primary GBM tumor cells were identified by their expression of the standard histopathological marker for astrocytoma (glioma) cells, GFAP." (PMID 22427929, 2012). "GFAP-Cre/RictorloxP/loxP mice developed gliomas reminiscent of human oligodendroglioma staining immunopositive for APC and GalC." (PMID 23077666, 2012). "We show here that glial fibrillary acidic protein Cre (GFAP-Cre) mediated conditional overexpression of Rictor is sufficient to induce intermediate-grade gliomas in mice." (PMID 23077666, 2012). "The tumor bulk in the PDGF-driven model of glioma expresses Olig2, while the GFAP-expressing cells are part of the tumor stroma." (PMID 22393407, 2012). "Double transgenic GFAP-Cre/RictorloxP/loxP mice developed multifocal infiltrating glioma containing elevated mTORC2 activity and typically involved the subventricular zone (SVZ) and lateral ventricle." (PMID 23077666, 2012). "The high (fifth) generation glioma implants were double-stained for GFAP and rat-specific nestin to evaluate the glial nature of the infiltrating host cells." (PMID 22539956, 2012). "We also examined the in vitro signaling and oncogenic properties of the derived tumors cell lines from both GFAP-Cre/RictorloxP/loxP and GFAP-EGFRvIII; GFAP-Cre/RictorloxP/loxP glial tumors." (PMID 23077666, 2012). "Transgenic GFAP-EGFRvIII; GFAP-Cre/RictorloxP/loxP mice exhibited a marked reduction in overall survival with 50% of animals developing gliomas by 4–6 weeks and all of the mice succumbing by 18 weeks." (PMID 23077666, 2012). "In sum, the mouse modeling experiments demonstrated a nearly 100% incidence of PDGF-induced gliomas arising from GFAP-expressing cells in all three locations in the brain, with an equal latency between SVZ and cortex and a longer latency in the cerebellum." (PMID 21931722, 2011).
glioma (continued). "GFAP was found to be increased in C6 glioma cells following ASH-WEX treatment, as observed by immunostaining and western blotting results." (PMID 20007262, 2011). "The immunohistochemical analysis of brain sections showed a significant increase in the GFAP expression in glioma compared to the normal hemisphere, same as it was observed in tumors, initiated by high grade glioma cultured cells." (PMID 23675241, 2011). "In order to analyze two different populations of glioma cells and hUCBSC inco-cultures, we used flow cytometry using two different markers, namely CD81 forhUCBSC and GFAP for glioma cells." (PMID 21455311, 2011). "We demonstrated that PDGF-induced gliomas can be derived from GFAP-expressing cells of the subventricular zone or the cortex (reactive astrocytes), thus validating the predictions of our mathematical model." (PMID 21931722, 2011). "Similar to our observation, earlier studies have also demonstrated the enhancement of GFAP protein level in response to i-Extract treatment in C6 glioma cell line." (PMID 22096544, 2011). "And the astrocyte marker GFAP is one of the major markers for the differentiated progeny of BTSCs, and GFAP expression is also increased after glioma cells differentiate into mature ones." (PMID 20716331, 2010). "C6 glioma differentiation was determined by morphological characterization, immunostaining and Western blot analysis on upregulation of GFAP and o p-STAT3 expression, and upregulation of intracellular cAMP." (PMID 21159181, 2010). "We have demonstrated that transduction efficiency of pG8-18 amplicon viruses was relatively high in proliferating GFAP-positive primary human glioma cells." (PMID 20942909, 2010). "Nonetheless, any neuronal inclusion within our glioma surgical samples is likely scant, at best, based on the abundance of GFAP staining." (PMID 19874583, 2009). "Here, the glioma surgical samples were stained with GFAP and Ki67 (a proliferation marker) to further confirm the identity and malignancy of the samples collected." (PMID 19874583, 2009). "These lines all grew as either stellate or bipolar cells, with some polygonal features, in monolayers, and the immunophenotypes were representative of high grade glial tumours, including expression GFAP, S100 and vimentin." (PMID 19365568, 2009). "In all these high-grade glioma cases, GFAP expression was detected with inter- as well as intra-glioma variation." (PMID 18398462, 2008). "We also studied the glioma cell multi-lineage differentiation potential in vivo by assessing GFAP and NSE/synaptophysin expression in the corresponding formaldehyde fixed specimens." (PMID 18398462, 2008). "Literature has shown, by and large, a negative correlation between the degree of malignancy and expression of GFAP and S100 protein in the majority of human gliomas." (PMID 15885136, 2005). "To overcome this problem, we have compared acutely established normal astrocytes and glioma cell cultures, mostly expressing the glial phenotype (as evidenced by the GFAP staining)." (PMID 16175187, 2005). "Further, these differentiated human glial tumour cells had long processes and a high content of glial fibrillary acidic protein similar to differentiated C6 glioma cells." (PMID 12373609, 2002).
glioma (continued). "The malignancy of gliomas is inversely correlated with the content of astrocyte-specific intermediate filament protein (GFAP)." (PMID 12373609, 2002). "High affinity GABA uptake, and GFAP in rat C6 glioma cultures, increased with increasing monolayer cell density, events probably mediated by an increase in the formation of cell-cell contacts at confluence." (PMID 6200130, 1984). "In summary, we present an unusual glioma with molecular features of pedHGG in an adult patient with bizarre epithelioid morphology and absence of GFAP‐expression imparting a diagnostic challenge." (PMID 40610013, 2026). "Immunohistochemical components, such as isocitrate dehydrogenase (IDH) mutations, GFAP (glial fibrillary acidic protein), ATRX (alpha-thalassemia/mental retardation, X-linked), and Ki-67, play a pivotal role in glioma diagnostic classification and risk stratification in prior literature." (PMID 41994675, 2026). "Olig2, GFAP, and vimentin are frequently used for glioma subtyping." (PMID 40362055, 2025). "When overexpressed in GFAP-expressing glioblastomas, the molecule creates a repellent effect on glioma cells, which may also play a role in TE-RMS cell organization and alignment." (PMID 41227295, 2025). "Finally, we selected the following seven indicators as the mIHC panel: IDHR132H, ATRX, EGFR, CDKN2A, HIP1R, GFAP (glial fibrillary acidic protein, marker of glioma cells), and DAPI (4ʹ,6‐diamidino‐2‐phenylindole, marker cell nucleus)." (PMID 40264576, 2025). "EZH2's role in regulating GFAP expression and astrocyte differentiation is of great interest, as it may offer insights into the molecular foundation of glioma formation and potential therapeutic strategies." (PMID 40022506, 2025). "GFAP-positive gliomas are known for their aggressive and invasive nature." (PMID 40575267, 2025). "Our prior experiments using glioma tissues demonstrated that post-expansion staining increases the intensity, continuity, and number of structures stained for vimentin, Iba1 and GFAP vs. pre-expansion staining." (PMID 38295184, 2024). "Thus, GFAP represents a potential prognostic biomarker and a candidate therapeutic target for gliomas." (PMID 38879494, 2024). "Many studies have shown the relationship between GFAP and neurological disorders such as gliomas." (PMID 38967699, 2024). "The cross‐reactivity of AE1/AE3 with other intermediate filament proteins, such as GFAP, observed in brain and glioma tissues could explain the widespread presence of keratin and GFAP positivity in specific retroperitoneal schwannomas." (PMID 39158355, 2024). "The role of GFAP in the development of glioma aggressiveness is complex." (PMID 39201395, 2024). "Finally, we examined ionized calcium binding adapter molecule 1 (Iba1) and GFAP in low-grade glioma tissue, again from cortex or white matter." (PMID 38295184, 2024). "Consequently, we found an increase in the expression of GFAP, but a decrease in the expression of Nestin and two markers of glioma stem cells, CD133 and CD44, indicating that low expression of OGDH promotes glioma cell differentiation." (PMID 39872214, 2024). "Upon the stimulation by serum, which has been known as an inducer of GIC differentiation, the GIC spheres increase cellular proliferation, motility, and adhesion to the culture dishes and upregulate the glial cell markers such as GFAP (glial fibrillary acid protein) and the glioma marker CD44." (PMID 38309500, 2024). "For example, our detection of an increased number of previously undetected double-labeled GFAP- and vimentin-positive cells in low-grade glioma tissue may represent a malignant cell subpopulation in these tumors, usually not detected histologically." (PMID 38295184, 2024).